ENSG00000200063
Synonyms: LOC124900399
Gene: Small nucleolar RNA gene on chromosome 17 (78,399,935 to 78,400,063, forward strand). Ensembl gene ENSG00000200063.
Gene Ontology:
Biological process: RNA processing
Cellular component: nucleolus
Homologues: Orthologues: mouse Snora30 (81% identical), rat Snora30 (81% identical), mouse Gm25133 (80% identical). Paralogues in human: SNORA30 (84% identical), SNORA37 (84% identical), SNORA30B (83% identical).